ANXA2 (annexin A2)
Diseases named in the same sentence as ANXA2 in open-access papers (continued):
Sharing a sentence is not in itself a finding about the gene and the disease.
endometrial cancer (21 papers, 2011 to 2025). Primary or metastatic malignant neoplasm involving the endometrium (mucous membrane that lines the endometrial cavity). "Expression levels of ANXA2 and HE4 were closely related to the malignant biological behavior of endometrial carcinoma, and ANXA2 was an independent risk factor for poor prognosis." (PMID 26362938, 2015). "ANXA2 expression in endometrial carcinoma tissues can be used as an independent risk factor for prognosis; the prognostic risk in patients with high expression of ANXA2 was eight times higher than patients with low expression." (PMID 26362938, 2015). "ANXA2 was an independent risk factor for the prognosis of endometrial carcinoma (p < 0.05, hazard ratio [HR] = 8.004)." (PMID 26362938, 2015). "As the most studied member of this family, ANXA2 is considered a possible cancer biomarker for several malignancies, including endometrial cancer." (PMID 39194522, 2024). "ANXA2, whose expression was highly correlated in both ET and ES, is predictive of recurrence in endometrial carcinoma." (PMID 38254014, 2024). "In our previous work, we demonstrated that ExoGAG is efficient in the isolation of EVs from plasma samples of endometrial cancer patients and identified ANXA2 protein as a possible EV-based prognostic biomarker in liquid biopsy." (PMID 36830940, 2023). "Lastly, researchers demonstrated Daunorubicin's capability to limit the growth of ANXA2 overexpressing cancer cells in a three-dimensional transendothelial migration process as well as an in vivo system of late Endometrial Cancer." (PMID 35685426, 2022). "Endometrial cancer cases with high staining scores of ANXA2 and HE4 had a shortened overall survival." (PMID 36354733, 2022). "According to our preliminary studies, ANXA2 is highly expressed in ovarian and endometrial cancers, and HE4 and ANXA2 also show co-localization in endometrial carcinoma." (PMID 31210752, 2019). "Multivariate Cox regression analysis showed that overexpression of ANXA2 and advanced FIGO staging were independent risk factors for the prognosis of endometrial carcinoma." (PMID 26362938, 2015). "The rate of positive expression of ANXA2 in endometrial carcinoma, atypical hyperplasia, and normal endometrium tissues was 95.2 % (80/84), 83.3 % (25/30), and 55.6 % (10/18), respectively." (PMID 26362938, 2015). "The study included 84 cases of endometrial carcinoma with positive expression of ANXA2 in well, moderately, and poorly differentiated groups (82.4 % [14/17], 95.8 % [23/24], and 100 % [43/43], respectively), which increased with the reduction in the degree of differentiation." (PMID 26362938, 2015). "Correlation analysis showed that there was a positive correlation between the expression of ANXA2 and HE4 in endometrial carcinoma (Spearman correlation coefficient RS = 0.228, p = 0.037)." (PMID 26362938, 2015). "ANXA2 and HE4 were expressed in 95.2 % and 85.7 % of the the endometrial carcinoma, respectively, which were significantly higher than normal endometrium (55.6 % and 16.7 %, both p < 0.05)." (PMID 26362938, 2015). "The expression of ANXA2 and HE4 protein in 84 endometrial carcinoma, 30 endometrial atypical hyperplasia, and 18 normal endometrial tissue samples were then measured using an immunohistochemical assay in paraffin embedded endometrial tissues." (PMID 26362938, 2015). "Does the interaction between ANXA2 and HE4 exist in endometrial carcinoma and promote its malignant biological behavior?" (PMID 26362938, 2015). "Results of western blot and immunocytochemical testing confirmed the expression of ANXA2 and HE4 in endometrial carcinoma cell lines (Ishikawa and HEC-1A)." (PMID 26362938, 2015). "Similar to ANXA2, the high expression rate of HE4 in stage III–IV endometrial carcinoma was 66.7 % (16/24), which was significantly higher than stage I–II (36.7 % [22/60]; p < 0.05)." (PMID 26362938, 2015). "Researches showed that, the expression of ANXA2 and HE4 were up-regulated in endometrial carcinoma, respectively." (PMID 26362938, 2015).
endometrial cancer (continued). "We evaluated the expression and the correlation relationship of ANXA2 and HE4 in endometrial carcinoma." (PMID 26362938, 2015). "Several molecular prognostic biomarkers have been studied in terms of survival and therapeutic response in women with endometrial cancer; hormone receptors, microRNAs, and other molecules have emerged as potentially useful biomarkers, including HER2, p21, HE4, PTEN, p27, ANCCA, and ANXA2." (PMID 34322276, 2019). "ANXA2 and HE4 co-localized in both endometrial tissues and endometrial carcinoma cells." (PMID 26362938, 2015). "ANXA2 and HE4 can be used as biomarkers to evaluate the prognosis of endometrial carcinoma." (PMID 26362938, 2015). "Annexin A2 (ANXA2) has been reported to be overexpressed in recurrent endometrial carcinoma, and the expression of human epididymis protein 4 (HE4) is upregulated in endometrial carcinoma." (PMID 26362938, 2015). "We revealed the co-localization of ANXA2 and HE4 in endometrial carcinoma." (PMID 26362938, 2015). "In summary, ANXA2 and HE4 were overexpressed in endometrial carcinoma." (PMID 26362938, 2015). "This study examined the expression of ANXA2 and HE4 in endometrial carcinoma cells using western blot and immunocytochemistry, and confirmed their interaction in endometrial carcinoma cells through co-immunoprecipitation and double-labelling immunofluorescence." (PMID 26362938, 2015). "Therefore, we hypothesized that ANXA2 interacted with HE4 to promote tumor invasion and metastasis in endometrial carcinoma." (PMID 26362938, 2015). "Additionally, in another analysis of 60 selected proteins in 10 endometrial cancer tissue samples with or without lymph node metastasis (LNM), 23 proteins were identified, with ANXA2 showing higher expression in samples with LNM." (PMID 39194522, 2024). "However, studies so far have not tested the expression of ANXA2 and HE4 in endometrial carcinoma, simultaneously." (PMID 26362938, 2015).
COVID-19 (20 papers, 2020 to 2025). A disease caused by infection with severe acute respiratory syndrome coronavirus 2. "Whereas some genes associated with fibrinolysis (F12 and ANXA2) showed increased expression, many were decreased in COVID-19 lung tissue relative to normal tissue." (PMID 34648357, 2021). "Thus, ANXA2 might serve as a potentially novel druggable target to attenuate COVID-19-associated thrombotic events." (PMID 38913740, 2024). "Moreover, recent reports have also shown that the elevated levels of anti-AnxA2 antibodies are observed among COVID-19 patients causing cytokine storm that may finally lead to systemic thrombosis, cell death, and non-cardiogenic pulmonary oedema." (PMID 34681689, 2021). "The identification of anti-AnxA2 antibodies in COVID-19 patients highlights its potential involvement in the pathogenesis of SARS-CoV-2 and related post-infection complications." (PMID 40943516, 2025). "Additional studies are warranted to further explore the impact of ANXA2 mechanism and identify potential therapeutic targets for COVID-19." (PMID 38913740, 2024). "The level of lung involvement, as measured by chest CT, was also found to be increased in COVID-19 patients with higher serum Annexin A2 levels." (PMID 37482693, 2023). "Autoantibodies against the lung protective protein Annexin-A2 correlated with patient mortality in COVID-19, suggesting a detrimental effect of certain autoantibody specificities in patients." (PMID 34504035, 2021). "Recent studies have provided insight why patients with severe COVID-19 develop hyperinflammation, among others due to improper IgG glycosylation, auto-antibodies against IFN and Annexin A2, and genetic polymorphisms." (PMID 34000622, 2021). "Given its critical protective roles, the levels of anti-AnxA2 antibodies among hospitalized COVID-19 patients highly predicted the mortality, indicating the importance of AnxA2 in the pathophysiology of SARS-CoV-2 infection." (PMID 34681689, 2021). "All genes (PPARG, CD36, STAB1, ITGAV, and ANXA2) downregulated in surviving patients with COVID-19 are related to cholesterol homeostasis." (PMID 34944005, 2021). "Recent investigations identified the presence of anti-AnxA2 autoantibodies in hospitalized COVID-19 patients." (PMID 34681689, 2021). "Interestingly, levels of one of these antibodies targeting Annexin A2 (ANXA2) have been readily elevated among hospitalized patients who died from COVID-19." (PMID 38913740, 2024). "Compared to uEVs isolated from the COVID-19-negative group and the COVID-19-positive mild-to-moderate severity group, Klotho protein enrichment was greater in the COVID-19-positive severe group where densitometric analysis was performed and Annexin A2 was used to assess lane loading." (PMID 39861814, 2024). "Similarly, recent investigations have found the presence of anti-Annexin A2 autoantibodies in hospitalized COVID-19 patients, with higher serum concentrations in patients who died from COVID-19 than in survivors." (PMID 37482693, 2023). "It is worth considering whether CXCR3 antagonists can be used in the treatment of patients with COVID-19 to decrease the concentration of Annexin A2." (PMID 37482693, 2023). "Monocytes from patients with COVID-19 express high levels of genes associated with inflammation including IL17RA, JAK-STAT-associated gene STAT6, and inflammatory protein-encoding genes TNFRSF1B and ANXA2." (PMID 36992700, 2023). "Anti-annexin A2 autoantibodies can be included in testing to predict severe COVID-19." (PMID 36341384, 2022). "Other studies have analyzed autoantibodies of different specificities, finding that protein antigens such as type I interferons, particular tissue associated antigens and cytokines or the lung protective protein Annexin-A2 correlate with COVID-19 severity or death in specific subgroups of patients." (PMID 34504035, 2021).
COVID-19 (continued). "In support of this hypothesis, it was also found that the level of autoantibodies against annexin A2, a protein important for fibrinolysis and the protection of lung tissue, predicts mortality in hospitalized COVID-19 patients." (PMID 34859078, 2021). "In addition, the ECM protein annexin A2 (ANXA2), which regulates secretion of surfactant-containing lamellar bodies in the type II pneumocyte, was also significantly downregulated in COVID-19." (PMID 33060566, 2020). "Thus, an elevated antibody response to ANXA2 in severe COVID-19 patients might interfere with the fibrinolytic process, causing undesirable thrombosis." (PMID 38913740, 2024). "Therefore, dysregulation of ANXA2 mechanism may contribute to thrombotic events observed in COVID-19." (PMID 38913740, 2024). "Finally, some studies reported higher levels of autoantibodies (such as against IFNγ, phospholipids, and annexin A2) in COVID-19 patients, suggesting that autoantibodies may drive the worsening of the disease." (PMID 35666101, 2022). "Furthermore, a glucocorticoid dexamethasone treatment, in severe COVID-19 patients, is known to induce anti-inflammatory AnxA1 and also enhances its translocation to cell membrane, could reduce the membrane deposition of AnxA2, making it unavailable for the virus entry and replication." (PMID 34681689, 2021). "Additionally, it has been observed in the hospitalized COVID-19 patients that there is a massive production of pro-inflammatory cytokines including IL-6, IL-1β, and TNFα, whose production is known to be stimulated by the concentrated AnxA2 at the plasma membrane in the heterotetramer form as A2T." (PMID 34681689, 2021). "A recent study demonstrated that one of such autoantibodies targeted Annexin A2 (ANXA2) was readily elevated among fatal cases, compared to those being hospitalized but not severe COVID-19 patients." (PMID 38913740, 2024). "Each EV preparation from the COVID-19 and non-COVID-19 group was found to be enriched in annexin A2 and HSP70 but not in the endoplasmic reticulum marker protein GRP94." (PMID 36675169, 2023). "Importantly, a recent study reported elevated levels of anti-ANXA2 antibodies among hospitalized COVID-19 patients who died when compared to those of non-critically affected patients." (PMID 38913740, 2024). "Common uEV biomarkers including annexin A2, HSP70, and CD9 were all present in each uEV preparation from the COVID-19-negative and COVID-19-positive participant groups, and the levels of each biomarker were generally comparable between the two groups." (PMID 39861814, 2024).
acute promyelocytic leukemia (17 papers, 2011 to 2025). An aggressive form of acute myeloid leukemia (AML), characterized by arrest of leukocyte differentiation at the promyelocyte stage, due to a specific chromosomal translocation t(15;17) in myeloid cells. "In humans, elevated AnxA2 expression in acute promyelocytic leukemia is linked to excessive fibrinolysis and bleeding." (PMID 40943516, 2025). "However, overexpression of Anxa2 causes hemorrhage in acute promyelocytic leukemia (APL), and its impairment or decrease leads to thrombosis." (PMID 37955107, 2023). "Moreover, ANXA2 has been correlated to the observed hyperfibrinolysis-dependent bleeding in acute promyelocytic leukemia." (PMID 27429043, 2016). "Furthermore, deregulation of annexin A2 expression in acute promyelocytic leukemia is an important mechanism for bleeding diathesis." (PMID 25641213, 2015). "The opposite effect, termed “annexinopathy”, has been described in acute promyelocytic leukemia (APL), in which overexpression of surface ANXA2 led to increased plasmin generation and hyperfibrinolysis." (PMID 38913740, 2024). "In humans, an increased annexin A2 expression in acute promyelocytic leukemia (APL) is associated with hyperfibrinolysis and bleeding while reduced annexin A2 expression impairs cell surface fibrinolysis and may constitute a risk factor for venous thromboembolism." (PMID 34566657, 2021). "Blast cells of patients with acute promyelocytic leukemia (APL) express AnxA2 to a high amount, which might explain the haemorrhagic complications observed in APL patients." (PMID 29914106, 2018). "There were reports that PDPN related to platelet aggregation and annexin A2 (ANXA2) related to hyperfibrinolysis were related to life-threatening coagulopathy in acute promyelocytic leukemia (APL) and non-APL, respectively." (PMID 35887121, 2022).
nasopharyngeal carcinoma (17 papers, 2013 to 2025). A carcinoma arising from the nasopharyngeal epithelium. "Associations of ANXA2 expression with clinicopathological characteristics in nasopharyngeal carcinoma patients." (PMID 35371986, 2022). "Another link between ANXA2 and HSP27 was reported in nasopharyngeal carcinoma in which the knockdown of ANXA2 activates the HSP27 pathway." (PMID 39562436, 2025). "The expression of annexin A2 (ANXA2) in nasopharyngeal carcinoma (NPC) cells induces the immunosuppressive response in dendritic cells; however, the oncogenic effect and clinical significance of ANXA2 have not been fully investigated in NPC cells." (PMID 26196246, 2015). "Proteomic analysis of nasopharyngeal carcinoma (NPC) revealed a consistent reduction in annexin A2 expression in all NPC patients and cell lines when compared with normal nasopharyngeal epithelium." (PMID 23519104, 2013). "In addition to HCC, the ANXA2-mediated immunosuppression phenotypes were observed in nasopharyngeal carcinoma cells and renal cell carcinoma." (PMID 34575275, 2021). "In the future, ANXA2 might be used as a target for new therapeutic strategies against nasopharyngeal carcinoma." (PMID 26196246, 2015). "The down-regulation of annexin A2 has been implicated in head and neck cancers primarily in esophageal squamous cell carcinoma (ESCC), nasopharyngeal carcinoma (NPC), and head and neck squamous cell carcinoma (HNSCC)." (PMID 23519104, 2013). "Annexin A2 (ANXA2) has been found to be involved in cancer proliferation, metastasis and prognosis; however, its exact role in nasopharyngeal carcinoma (NPC) radioresistance remains unknown." (PMID 35371986, 2022).
osteosarcoma (17 papers, 2009 to 2025). A usually aggressive malignant bone-forming mesenchymal neoplasm, predominantly affecting adolescents and young adults. "In future, studies elucidating the molecular mechanisms underlying S100 A16-mediated regulation of ANXA2 expression could provide critical insights into the pathogenesis of osteosarcoma progression." (PMID 40481236, 2025). "In our study, we identified that S100 A16 promotes the progression of osteosarcoma through its interaction with ANXA2." (PMID 40481236, 2025). "In osteosarcoma, studies have shown that high-level expression of ANXA2 promotes the proliferation, migration, and invasion of tumor cells." (PMID 40481236, 2025). "This study shows that S100 A16 is significantly upregulated in osteosarcoma and promotes cell proliferation, migration, and invasion by regulating ANXA2 and activating the PI3 K/AKT signaling pathway." (PMID 40481236, 2025). "Further research indicates that S100A16 activates the PI3K/AKT signaling pathway by regulating the expression of ANXA2, thereby promoting the development of osteosarcoma." (PMID 40481236, 2025). "WB and qRT-PCR analyses confirmed that ANXA2 expression was significantly upregulated in osteosarcoma tissues compared to normal tissues." (PMID 40481236, 2025). "Overexpression of S100 A16 increases the levels of ANXA2, thereby enhancing the proliferation, migration, invasion, and anti-apoptotic capabilities of osteosarcoma cells." (PMID 40481236, 2025). "In osteosarcoma, the ANXA2 mRNA and protein levels are inversely correlated with metastatic potential in a subset of human osteosarcoma tumor specimens." (PMID 24591759, 2014). "In conclusion, our study reveals the mechanism of S100 A16 in osteosarcoma and suggests that targeting the S100 A16/ANXA2/PI3 K/AKT axis could be a feasible strategy for osteosarcoma therapy." (PMID 40481236, 2025). "This study demonstrated, surprisingly, that ANXA2 is involved in the differentiation-induced mineralization process of osteoblastic cells in vitro and may decrease osteosarcoma aggressiveness." (PMID 24591759, 2014). "Cellular experiments showed that the S100A16 promoted osteosarcoma progression by activating the PI3K/AKT signaling pathway, and upregulated expression of ANXA2, a crucial protein in occurrence and development of tumors." (PMID 40481236, 2025). "Functional cellular assays demonstrated that S100 A16 promotes osteosarcoma cell proliferation and invasion by activating the PI3 K/AKT pathway via ANXA2." (PMID 40481236, 2025). "Annexin 2 (ANXA2), another gene indirectly involved with the osteoclastic activity and bone resorption, was significantly expressed in poor chemotherapy response of osteosarcoma patients." (PMID 37107591, 2023). "Downregulation of miR-143 promotes osteosarcoma cell invasion through MMP-13 upregulation, and silencing of miR-133a reduces the malignancy of CD133high osteosarcoma-initiating cell population through restoring the expression of multiple target genes (SGMS2, UBA2, SNX30, and ANXA2)." (PMID 25912304, 2015). "Gillette and Nielsen-Preiss demonstrated that over-expression of AnxA2 in human osteosarcoma cells facilitates the terminal stages of osteogenic differentiation, specifically matrix mineralization, although if AnxA2 exerted a role prior to mineralization was not examined." (PMID 25222280, 2014).